MIR653 (microRNA 653)
Synonyms: hsa-mir-653; MIRN653; mir-653
Gene: MicroRNA gene on chromosome 7 (93,482,760 to 93,482,855, reverse strand). Ensembl gene ENSG00000208014.
Gene Ontology:
Biological process: miRNA-mediated post-transcriptional gene silencing
Cellular component: RISC complex
Homologues: Orthologues: chimpanzee ptr-mir-653 (100% identical), macaque mml-mir-653 (99% identical), dog MIR653 (90% identical), guinea pig MIR653 (80% identical), rabbit MIR653 (51% identical).